CCL20 (C-C motif chemokine ligand 20)
Description:
Acts as a ligand for C-C chemokine receptor CCR6. Signals through binding and activation of CCR6 and induces a strong chemotactic response and mobilization of intracellular calcium ions. The ligand-receptor pair CCL20-CCR6 is responsible for the chemotaxis of dendritic cells (DC), effector/memory T-cells and B-cells and plays an important role at skin and mucosal surfaces under homeostatic and inflammatory conditions, as well as in pathology, including cancer and various autoimmune diseases. CCL20 acts as a chemotactic factor that attracts lymphocytes and, slightly, neutrophils, but not monocytes. Involved in the recruitment of both the pro-inflammatory IL17 producing helper T-cells (Th17) and the regulatory T-cells (Treg) to sites of inflammation. Required for optimal migration of thymic natural regulatory T cells (nTregs) and DN1 early thymocyte progenitor cells (By similarity). C-terminal processed forms have been shown to be equally chemotactically active for leukocytes. Positively regulates sperm motility and chemotaxis via its binding to CCR6 which triggers Ca2+ mobilization in the sperm which is important for its motility. Inhibits proliferation of myeloid progenitors in colony formation assays. May be involved in formation and function of the mucosal lymphoid tissues by attracting lymphocytes and dendritic cells towards epithelial cells (By similarity). Possesses antibacterial activity towards E.coli ATCC 25922 and S.aureus ATCC 29213.
Synonyms: MIP-3-alpha; LARC; MIP3A; SCYA20; MIP-3a; exodus-1; ST38; CKb4; Exodus
Tractability: Small molecule: a structure with a bound ligand is known. Antibody: UniProt places it where antibodies can reach, with high confidence; its Gene Ontology location is reachable by antibodies, with high confidence; UniProt predicts a signal peptide or a membrane-spanning region. PROTAC: its protein half-life has been measured.
Gene: Protein-coding gene on chromosome 2 (227,805,739 to 227,817,564, forward strand). Ensembl gene ENSG00000115009.
Subcellular location: Secreted
Pathways (Reactome):
Signal Transduction: Chemokine receptors bind chemokines; G alpha (i) signalling events
Immune System: Interleukin-10 signaling
Gene Ontology:
Molecular function: CCR6 chemokine receptor binding; protein binding; chemokine activity; cytokine activity
Biological process: calcium-mediated signaling; cell chemotaxis; chemotaxis; positive regulation of T cell migration; cell-cell signaling; immune response; inflammatory response; signal transduction; T cell migration; thymocyte migration
Cellular component: extracellular region
Genetic constraint (gnomAD): Loss-of-function variants: 0 observed, 0.41 expected, observed/expected ratio (o/e) 0, 90% interval 0 to 1.85. That is too few expected variants to judge how well the gene tolerates losing a copy. Missense variants: 7 observed, 12.38 expected, observed/expected ratio (o/e) 0.57, 90% interval 0.32 to 1.06. Synonymous variants: 7 observed, 7 expected, observed/expected ratio (o/e) 1, 90% interval 0.56 to 1.75.
Homologues: Orthologues: chimpanzee CCL20 (99% identical), macaque CCL20 (82% identical), guinea pig CCL20 (72% identical), rabbit CCL20 (71% identical), mouse Ccl20 (60% identical). Paralogues in human: CCL21 (30% identical), CCL16 (29% identical), CCL26 (26% identical), CCL3 (26% identical), CCL3L3 (26% identical), CCL4 (26% identical), XCL1 (26% identical), XCL2 (26% identical), CCL19 (25% identical), CCL22 (25% identical), CCL23 (25% identical), CCL25 (25% identical), and 14 more.
Diseases named in the same sentence as CCL20 in open-access papers:
CCL20 is named in the same sentence as 421 diseases in open-access papers, as found by Europe PMC text mining. Sharing a sentence is not in itself a finding about the gene and the disease. The quoted sentences say what the papers report.
psoriasis (132 papers, 2009 to 2026). An autoimmune condition characterized by red, well-delineated plaques with silvery scales that are usually on the extensor surfaces and scalp. "These mice showed upregulated expression of IL-17 and TNF-α signaling-related cytokines and chemokines (e.g., TNF, Ccl20, Cxcl1, IL-22, IL-23a) and are more susceptible to psoriasis upon induction." (PMID 41583484, 2025). "Here we show reduced CD200, and CD200R1 signaling in PN skin which, in a mouse model of psoriasis, results in enhanced severity associated with increased skin thickening, CCL20 levels, and neutrophil recruitment." (PMID 35759230, 2022). "There are 122 differentially upregulated and 210 differentially downregulated genes in common between the activated + fisetin and the activated group alone, notably many psoriasis-associated genes such as CCL20, IL36G, IL23A and NFKBIZ." (PMID 36741386, 2022). "CCL20, is a key disease‐driving chemokine, which is profoundly upregulated in psoriasis and is crucial for recruiting pathogenic T cells." (PMID 35759230, 2022). "They introduced Card14ΔE138K/A mutations in mice with psoriasis and found an up-regulation of pro-inflammatory cytokines, IL-23, IL-19, IL-22 and IL-17; chemokines Cxcl1, Ccl20, and Cxcl2; and antimicrobial peptides, Lcn2 and Defb4." (PMID 36012602, 2022). "CCL20 is a chemokine implicated in a wide range of inflammatory responses, such as those during airway irritation, irritable bowel disease, psoriasis, cancer, and neuroinflammation." (PMID 36167782, 2022). "Previous studies have shown that CCL20 S64C alleviates the inflammatory response in psoriasis-like models induced by IL-23, and have been associated with reduced accumulation of CCR6+ IL-17-producing γδT cells in the epidermis." (PMID 33732249, 2021). "A previous study revealed that scratch injury on keratinocytes upregulates CCL20 production, which is implicated in the Koebner phenomenon characteristically seen in psoriasis patients." (PMID 31936670, 2020). "We identified IL-17 as the main Th17 cell derived cytokine that induced upregulation of the genes encoding NF-kappa-B inhibitor zeta (NFKBIZ) and psoriasis-associated mediators, including CCL20, IL36G, and the antimicrobial peptide human β Defensin 2 (DEFB4A)." (PMID 30972071, 2019). "The expression of many genes known to be associated with psoriasis, including Lce3f, Sprr2b, Krt15, S100a8, S100a9, Il17a, Il17f, Il18, Il20, Il22, and Ccl20, was downregulated in the skin of IMQ-treated Camk4−/− mice compared with those of IMQ-treated Camk4+/+ mice." (PMID 35869084, 2022). "In this case, VER application may amplify psoriasis-associated inflammation due to its mechanism of NF-κB activation and positive expression of CCL20, among others." (PMID 34834106, 2021). "Helper CD8+ T cells may induce the secretion of a distinct repertoire of chemokines by their adjacent cells, such as CCL20 from keratinocytes, which is associated with progressing psoriasis." (PMID 33311473, 2020). "CCL20 produced from IL-17A-stimulated keratinocytes recruits IL-17A-producing Th17 cells and ILC3s and accelerates the feed-forward vicious cycle, which causes fully developed psoriasis." (PMID 32070069, 2020). "In both IL-23- and IMQ-induced psoriasis animal models, dermal γδT-cells mainly infiltrate the dermis and then migrate to the epidermis, which is associated with IL-17 expression levels in psoriatic lesions and highly dependent on the CCL20/CCR6 axis." (PMID 32355189, 2020). "In addition, NF-κB activity is regulated by CARD14, a protein of “signalosome” complex involved in activation of innate immunity molecules (i.e., IL-36γ, CXCL8, and CCL20), whose gene shows different allelic variants associated to psoriasis." (PMID 30034395, 2018). "The T-cell chemoattractant chemokine CCL20 has been associated with psoriasis." (PMID 27568525, 2017).
psoriasis (continued). "Normal human keratinocytes were found to constitutively bear the IL-17 receptor (IL-17R) and they are able to produce several IL-17-induced inflammatory and immune-related mediators implicated in psoriasis pathogenesis (e.g. IL-8, CCL20, S100A12, CXCL1, and CXCL2)." (PMID 24587313, 2014). "In addition, treating cultured human keratinocytes with IL-17 was shown to cause dose- and time-dependent up-regulation of CCL20, leading to the speculation that inhibition of this process may contribute to the resolution of psoriasis." (PMID 21311769, 2011). "Across all conditions, migration of inserted T cells towards the epidermis and the secretion of psoriasis-associated cytokines (IFN-γ, IL-17, TNF-α, IL-1β, CCL20, IL-6, and IL-10) was observed." (PMID 42039187, 2026). "A modest but statistically significant positive correlation between CCL20 levels in L skin and plasma indicated CCL20 as a potential plasma biomarker for severe psoriasis." (PMID 40943056, 2025). "Our results show that protein levels of multiple proteins (32/71) were upregulated at baseline in the lesional skin compared to non‐lesional skin, including three key biomarkers of the psoriasis disease pathology (IL‐17A, CCL20 and TNFα)." (PMID 40970551, 2025). "It has been shown that human umbilical cord MSC-derived exosomes (hUCMSCs-Exo) are able to alleviate psoriasis-like skin inflammation by suppressing the expression of IL-17, IL-23, CCL20, and STAT3." (PMID 40906403, 2025). "CCL20, known as Macrophage Inflammatory Protein-3α (MIP-3α) or Liver and Activation-Regulated Chemokine (LARC), is a chemokine that is particularly important in psoriasis." (PMID 40343299, 2025). "Due to increased expression of chemokine receptors, skin-homing T cells of psoriasis patients respond to lower concentrations of chemokines, including CCL20, and exhibit stronger chemotactic responses compared to T cells of healthy individuals." (PMID 38642273, 2024). "The results demonstrated that CCL20, ADAMDEC1, and CXCL13 exhibited strong diagnostic performance in both BC and psoriasis." (PMID 38605947, 2024). "The expression of chemokines and their receptors are regulated by psoriasis-associated cytokines, including IL-17 which upregulates CCL2, CCL7, CCL20, and CXCL1, or IFN-γ which upregulates CXCL9 and CXCL10." (PMID 38642273, 2024). "The heatmaps revealed an increase in several classic proinflammatory cytokines such as Tnf, Il6, Il1a, Il23α and a small number of chemokines, including Ccl19, Ccl20, Cxcl13, and Cxcl5, which are typically elevated in psoriasis patients, in CD169+ macrophages." (PMID 38891893, 2024). "Remarkably, treatment of 17A-Lytaca markedly decreased the mRNA expression of IL-17A and its downstream psoriasis-related inflammatory cytokines in the skin lesion, including IL-6, CCL-20, and IL-22, compared with the positive group." (PMID 38396109, 2024). "In psoriasis, IL-17 activated keratinocytes to produce chemokinesattracting neutrophilic granulocytes and CCL20 attracting myeloid dendritic cells, which strengthened tissue inflammation." (PMID 39480805, 2024). "CCR6+ T cells and CCL20 are abundant in the psoriatic skin of human psoriasis and experimental psoriasiform dermatitis." (PMID 37092451, 2023). "Signaling via the CCL20/CCR6 axis was shown to be more pronounced in the lesional skin of human psoriasis and in mouse models of psoriasis-like skin inflammation." (PMID 37049538, 2023). "The activated JNK pathway in keratinocytes can mediate the recruitment of immune cells in psoriasis by regulating the production of inflammatory cytokines/chemokines, such as IL-6, IL-8, IL-23, IFNγ and TNFα, and CCL20 and hβD-2." (PMID 38008779, 2023). "The coordination between CCR6 and its ligand CC motif chemokine ligand 20 (CCL20) is deeply involved in the pathogenesis of various diseases, such as cancer, psoriasis, and autoimmune diseases." (PMID 37218898, 2023).
psoriasis (continued). "As well as in psoriasis, the enrichment of IL-17A-producing immune cells leads to produce high levels of IL-17A, which further stimulates keratinocytes producing CCL20, CXCL8, and IL-36γ to recruit more IL-17A-producing immune cells and neutrophils." (PMID 35069008, 2022). "The levels of chemokines such as CXCL8 and CCL20 were dramatically increased in the TNF-α/IL-17/IFN-γ-induced HaCaT psoriasis model." (PMID 36015080, 2022). "SerpinB7 knockdown in HaCaT cells drastically increased the expression of psoriasis-related chemokines (CCL20, CCL27, CXCL1, CXCL2) and antimicrobial peptides LL37 and S100A8 in the M5-stimulated in vitro psoriatic model." (PMID 35864103, 2022). "In turn, IL-17A promotes keratinocytes to produce CCL20, and Th17 cells can also produce CCL20, which forms positive feedback in the pathogenesis of psoriasis." (PMID 36620087, 2022). "Inflammatory cells infiltrate the skin and form a positive inflammatory loop to mediate the occurrence and development of psoriasis, among which CCL20 plays a key role." (PMID 35966027, 2022). "Compound 1 also clearly inhibited the phosphorylation of STAT3, which regulates the expression of cytokines, and CCL20 chemokines in TNF-α /IL-17A/ IFN-γ induced the psoriasis condition." (PMID 36015080, 2022). "IL-17, alone or synergistically with TNF-α acting on keratinocytes, results in the transcription of many psoriasis-related genes, including CCL20, CXCL1, -2, -3, and -8 chemokines." (PMID 35216231, 2022). "Keratinocytes express CXCL1, CXCL2, CXCL8, and CCL20, which recruit neutrophils and are up-regulated in psoriasis to increase inflammation." (PMID 36077018, 2022). "CCL20 and IL-8 secreted by keratinocytes play important roles in psoriasis, including the activation and chemotaxis of Th17 cells and neutrophils." (PMID 36035154, 2022). "Obesity, being associated with an increase in visceral fat, is characterized by low-grade inflammatory status with production of several of cytokines and chemokines such as beta-defensins 2/3, CXCL8/10, and CCL20, which promote the development of psoriasis." (PMID 35276950, 2022). "The clearance of CCL20 has been proven to significantly decrease the infiltration of γδ T cells in mice and relieve the symptoms of psoriasis." (PMID 35966027, 2022). "Chemoattractant CCL20 recruits dendritic and T cells stimulating inflammation in the skin and was upregulated in psoriasis and was produced under control of NF-kB signaling in keratinocytes." (PMID 34834106, 2021). "In vitro studies showed that the expression of C-C motif chemokine ligand 20 (CCL20) (an essential chemoattractant molecule in psoriasis) was induced in normal murine epidermal keratinocytes when the medium was supplemented with ethanol." (PMID 34067223, 2021). "Keratinocytes in disease-naïve sites of psoriasis upregulate the expression of chemokines, such as CCL20 upon stimulation by skin commensal fungi." (PMID 34501272, 2021). "The interaction between CCL20 and CCR6 is an indispensable pathogenic mechanism of autoimmune disorders, including psoriasis, and it is considered a distinct therapeutic target." (PMID 34361983, 2021). "CCL20 compels the infiltration of Th17 cells, which then produce more CCL20, ultimately creating an inflammatory positive feedback loop that drives psoriasis pathology." (PMID 34639182, 2021). "In contrast, the anti-bacterial peptide S100A7 and the chemokine CCL20 that are frequently used as markers of psoriasis were moderately changed in the model group." (PMID 33986690, 2021). "IL-17A also upregulated CCL20 production via EGFR activation and further potentiated scratch-induced CCL20 production, suggesting that epidermal CCL20 production is an integral part in the pathogenesis of psoriasis and Koebnerization." (PMID 31936670, 2020).
psoriasis (continued). "In a murine psoriasis model generated by intradermal IL-23 injection, treatment with an anti–CCL20 antibody significantly reduced the recruitment of CCR6+ cells and attenuated IL-23–induced psoriasiform dermatitis." (PMID 31936670, 2020). "In psoriasis, keratinocytes recruit dendritic cells via CCL20, and the production of IL-23A by keratinocytes and dendritic cells recruits and activates IL-17A-producing Th17 cells, CD8+ T cells, innate lymphoid cells (ILC), and γδ T cells." (PMID 31964744, 2020). "We have previously demonstrated an upregulated production of CCL20 following scratch injury in keratinocytes and proposed a potential link to the Koebner phenomenon in psoriasis." (PMID 31936670, 2020). "Overexpression of psoriasis-associated mutants of CARD14 in keratinocytes results in enhanced NF-κβ activation and upregulation of psoriasis-associated chemokines (e.g., CCL20 and IL-8)." (PMID 32252279, 2020). "Epidermal keratinocytes represent a rich source of C-C motif chemokine 20 (CCL20) and recruit CCR6+ interleukin (IL)-17A–producing T cells that are known to be pathogenic for psoriasis." (PMID 31936670, 2020). "Herein, we have shown increased expression of transcripts for TNF-α, of which the involvement in psoriasis is well-established, as well as CCL20 and hBD2, which are known to activate Th17 chemotaxis through CCR6." (PMID 28708859, 2017). "CCL20 is up-regulated in psoriasis and in activated keratinocytes of cutaneous injury and of UVB irradiated skin." (PMID 27442430, 2016). "By contrast, Th1 cells likely participate in earlier stage of psoriasis pathogenesis by inducing CCL20 and IL-23 production by myeloid dendritic cells, thus playing a role upstream of the proinflammatory cascade controlled by IL-23/Th17 axis." (PMID 27595115, 2016). "Transfection of keratinocytes with the psoriasis-associated mutations in CARD14 resulted in increased NF-κB activity, as well as transcription of pro-inflammatory genes, such as CCL20 and IL-8." (PMID 25369198, 2014). "Increased CCL20 expression in keratinocytes of patients with psoriasis has been reported, and the contribution of CCR6-positive Th17 cells to the pathology of inflammatory diseases has been suggested clinically." (PMID 25172034, 2014). "Previous studies had described CARD14 expression in keratinocytes, and transfection of psoriasis-associated CARD14 mutations in KCs resulted in upregulated NF-κB signaling, and increased expression of IL-8 and CCL20." (PMID 25369198, 2014). "A role for TNFα in Ccl20 expression has also been demonstrated in dermal lesions of psoriasis patients based on treatment with the TNFα antagonist infliximab." (PMID 24823369, 2014). "CCL20 has been reported in many immune mediated inflammatory diseases, such as rheumatoid arthritis, psoriasis, asthma and inflammatory bowel disease." (PMID 23823618, 2013). "There is abundant CCL20 protein staining in psoriasis, which is chemotactic for CCR6+ immature DCs and Th17 cells." (PMID 22348003, 2012). "Together with our recent finding, our data stressed a pivotal role of the NF-κB signaling pathway in the PL-mediated induction of CCL20 and IL-23, and suggest that NF-κB signaling is critical for the induction of CCL20 and IL-23 in psoriasis." (PMID 21311769, 2011). "In psoriasis, CCL20 produced at sites of skin inflammation is a chemoattractant for skin-homing cutaneous lymphocyte-associated antigen (CLA)+CCR6+ T cells and Th17 cells in the circulation." (PMID 21311769, 2011). "CCL-20 was weakly expressed in normal human skin but was strongly augmented in some inflamed diseases, such as atopic dermatitis and psoriasis." (PMID 21050487, 2010). "Furthermore, intradermal injection of plasmin, which activates NF-κB signaling and induces the production of inflammatory factors, including CCL20 and IL-23, results in psoriasiform skin inflammation with several features of human psoriasis in mice." (PMID 41226338, 2025).